PKD2 (polycystin 2, transient receptor potential cation channel)
Diseases named in the same sentence as PKD2 in open-access papers (continued):
Sharing a sentence is not in itself a finding about the gene and the disease.
autosomal dominant polycystic kidney disease (continued). "Another case is that the autosomal dominant polycystic kidney disease in humans often inherits heterozygous loss-of-function mutations in either PKD1 (polycystic kidney disease-1) or PKD2 (polycystic kidney disease-2), while the mice displays only very mild cystic disease in the same situation." (PMID 32586408, 2020). "Autosomal dominant polycystic kidney disease is defined as an inherited disorder characterized by renal cyst formation due to mutations in the PKD1 or PKD2 gene, whereas tuberous sclerosis complex is an autosomal dominant neurocutaneous syndrome caused by mutation or deletion of the TSC2 gene." (PMID 31870441, 2019). "Mutations in PKD2 account for 10–15% of patients with autosomal dominant polycystic kidney disease (ADPKD), a common genetic disorder with a population prevalence of ∼1∶1000 that is characterized by formation of cysts in various organs, including kidneys, liver and pancreas." (PMID 22802962, 2012). "Autosomal dominant polycystic kidney disease (ADPKD) is a common inherited disorder caused by mutations in PKD1 or PKD2." (PMID 41501598, 2026). "Until recently, the role of PKD1 and PKD2 has been associated with the pathogenesis of the kidney since mutations in these genes cause autosomal dominant polycystic kidney disease (ADPKD)." (PMID 40299470, 2025). "Renal polycystins (PKD1 and PKD2) are ion channel subunits with associated genetic variants that cause autosomal dominant polycystic kidney disease (ADPKD) (1, –3)." (PMID 40504156, 2025). "PKD2 loss-of-function mutation induces several craniofacial abnormalities, which are also detected in autosomal dominant polycystic kidney disease (ADPKD) patients." (PMID 38791330, 2024). "Autosomal dominant polycystic kidney disease (ADPKD) results from mutations in the PKD1 or PKD2 genes and affects between 1:400–1:1000 individuals worldwide, making it the leading, life-threatening monogenic illness." (PMID 39314240, 2024). "The identification of mutations in the PKD1 or PKD2 genes holds significant prognostic value, particularly in families with no known history of Autosomal Dominant Polycystic Kidney Disease (ADPKD)." (PMID 39457385, 2024). "Autosomal dominant polycystic kidney disease (ADPKD) is the most common renal genetic disorder caused mainly by mutations of the PKD1 or PKD2 gene, which code for polycystin-1 (PC1) or polycystin-2 (PC2), respectively." (PMID 38912583, 2024). "Autosomal dominant polycystic kidney disease (ADPKD) is a hereditary kidney disorder caused by mutations in the PKD1 or PKD2 genes encoding polycystin 1 (PC1) or PC2 and is characterized by the growth of excessive cysts in the kidneys." (PMID 39203885, 2024). "Mutations in PKD1 and PKD2 cause autosomal dominant polycystic kidney disease (ADPKD), which is characterized by the formation of fluid‐filled cysts in the kidney." (PMID 38561249, 2024). "For example, mutations in the PKD1 and PKD2 genes are the main cause of autosomal dominant polycystic kidney disease (ADPKD), which leads to cyst formation and gradual kidney failure." (PMID 39728069, 2024). "Mutations in PKD2 can lead to autosomal dominant polycystic kidney disease (ADPKD), a multisystem and progressive adult-onset genetic disorder characterized by the formation of fluid-filled cysts and increased kidney volume." (PMID 39451240, 2024). "Autosomal dominant polycystic kidney disease (ADPKD) is a hereditary kidney disorder mostly caused by mutations in PKD1 or PKD2 genes." (PMID 37152951, 2023). "Autosomal dominant polycystic kidney disease (ADPKD) can often be attributed to mutations of the PKD2 gene." (PMID 36613622, 2022). "Evidence supporting PC-1 and PC-2 interdependency includes that mutations in either Pkd1 or Pkd2 result in autosomal dominant polycystic kidney disease (ADPKD), the most prevalent monogenic disorder in humans." (PMID 35229718, 2022).
autosomal dominant polycystic kidney disease (continued). "Mutations in polycystin-1 encoding gene PKD1 or polycystin-2 encoding gene PKD2 were commonly seen in cases of Caroli disease associated with autosomal dominant polycystic kidney disease (ADPKD)." (PMID 35741793, 2022). "Autosomal dominant polycystic kidney disease (ADPKD) is caused by germline mutations of PKD1 or PKD2 on one allele and a somatic mutation inactivating the remaining normal allele." (PMID 34315885, 2021). "Autosomal dominant polycystic kidney disease (ADPKD) is caused by loss of function of PKD1 (polycystin 1) or PKD2 (polycystin 2)." (PMID 34199520, 2021). "Mutations in Pkd2 lead to Autosomal Dominant Polycystic Kidney Disease (ADPKD), the most prevalent monogenic human disease worldwide." (PMID 32364494, 2020). "Variants in human PKD2 account for ∼15% of cases of autosomal dominant polycystic kidney disease (ADPKD), a common ciliopathy that is characterized by progressive cyst development, which ultimately causes renal failure." (PMID 33199522, 2020). "The autosomal dominant polycystic kidney disease (ADPKD) is mainly caused by the mutations in the PKD1 or PKD2 genes." (PMID 32823757, 2020). "Autosomal Dominant Polycystic Kidney Disease (ADPKD) occurs due to mutations in Pkd1 or Pkd2 and is the most prevalent monogenic human disease worldwide, affecting 1 in 400–1000 individuals." (PMID 32364494, 2020). "Polycystin-1 (PC-1) and 2 (PC-2) are the products of the PKD1 and PKD2 genes, which are mutated in Autosomal Dominant Polycystic Kidney Disease (ADPKD)." (PMID 31719603, 2019). "Autosomal dominant polycystic kidney disease (ADPKD), which is defined as an inherited disorder characterized by renal cyst formation, is caused by dysfunction of polycystin 1 or polycystin 2, which leads to mutations in the PKD1 or PKD2 gene, respectively." (PMID 31870441, 2019). "PKD2 mutations cause Autosomal Dominant Polycystic Kidney Disease (ADPKD) and affect many cellular pathways." (PMID 31492868, 2019). "Mutations in PKD2 account for ~15% of cases of individuals afflicted with Autosomal Dominant Polycystic Kidney Disease (ADPKD)." (PMID 30004384, 2018). "For example, PKD1 forms a complex with PKD2 and mutations in either of these proteins cause Autosomal Dominant Polycystic Kidney Disease (ADPKD), which is the most frequent potentially-lethal single-gene disorder in humans." (PMID 28271061, 2017). "Autosomal dominant polycystic kidney disease (ADPKD) is the most common inherited kidney disorder mainly caused by mutation in PKD1/PKD2." (PMID 27782177, 2016). "Mutations in PKD2 account for 10–15% of the autosomal dominant polycystic kidney disease (ADPKD), a prominent inherited disorder that affects 12.5 million people worldwide." (PMID 25861040, 2015). "Mutations in TSC1 or TSC2 cause the tuberous sclerosis complex (TSC), while mutations in PKD1 or PKD2 cause autosomal dominant polycystic kidney disease (ADPKD)." (PMID 26077033, 2015). "Typically, the functions of PC1 and PC2 are interdependent and concordant, as evidenced by common Autosomal Dominant Polycystic Kidney Disease (ADPKD) phenotype caused by inactivation of either PKD1 or PKD2." (PMID 25464512, 2014). "Loss of PKD1 or PKD2 function in renal tubular epithelial cells causes Autosomal Dominant Polycystic Kidney Disease (ADPKD) that is the result of abnormal cell proliferation and cell polarity and leads to cystic kidney disease." (PMID 23029375, 2012). "Autosomal dominant polycystic kidney disease (ADPKD) shows remarkable variability in clinical severity, even among individuals with the same PKD1 or PKD2 pathogenic variants." (PMID 41502815, 2026). "Autosomal dominant polycystic kidney disease (ADPKD), caused by mutations in PKD1 or PKD2, is characterized by progressive and exponential enlargement of renal and hepatic cysts." (PMID 41677660, 2026). "Autosomal-dominant polycystic kidney disease (ADPKD) is primarily of adult-onset and caused by pathogenic variants in PKD1 or PKD2." (PMID 41677782, 2026).
autosomal dominant polycystic kidney disease (continued). "Genetic risk stratification in autosomal dominant polycystic kidney disease relies primarily on identification of pathogenic variants in PKD1 and PKD2, which account for the vast majority of cases." (PMID 41597516, 2026). "Autosomal Dominant Polycystic Kidney Disease (ADPKD), caused by pathogenic variants in PKD1 and PKD2, is the most common monogenic cause of kidney failure." (PMID 41006799, 2026). "Autosomal dominant polycystic kidney disease (ADPKD) is usually caused by variants in the PKD1 and PKD2 genes." (PMID 39883360, 2025). "In 1999, LOV-1 and PKD-2 were shown to localize to cilia in Caenorhabditis elegans, the human homologs of which are responsible for autosomal dominant polycystic kidney disease (ADPKD)." (PMID 41164956, 2025). "Germline mutations in PKD1 and PKD2 genes cause autosomal dominant polycystic kidney disease (ADPKD), characterized by the enlargement of renal tubules and the formation of isolated fluid-filled cysts within the kidney and other organs such as the liver and pancreas." (PMID 39900437, 2025). "Autosomal dominant polycystic kidney disease (ADPKD) is the most common hereditary kidney disease, caused by mutations in either the PKD1 or PKD2 gene, and is characterized by the development of multiple renal cysts." (PMID 41425591, 2025). "Autosomal dominant polycystic kidney disease (ADPKD), which is caused mainly by mutations in the PKD1 or PKD2 genes, is a genetic disorder characterized by the growth of cysts and decreased kidney function." (PMID 41254555, 2025). "Autosomal dominant polycystic kidney disease (ADPKD), caused by PKD1/PKD2 mutations, features renal and extrarenal manifestations including valvulopathies and left ventricular hypertrophy (LVH), which increase mortality." (PMID 41195291, 2025). "Autosomal dominant polycystic kidney disease (ADPKD) is the most common inherited kidney disorder, typically presenting in adulthood and most often caused by PKD1 or PKD2 mutations." (PMID 41450889, 2025). "Mutations in PKD2 contribute to approximately 15–20% of Autosomal Dominant Polycystic Kidney Disease (ADPKD) cases, the most common inherited monogenic renal disease worldwide, characterized by clusters of fluid-filled cysts in both kidneys, associated with a gradual decline in renal function." (PMID 41465431, 2025). "Autosomal dominant polycystic kidney disease (ADPKD) is the most common inherited cystic kidney disease (common causative mutations involve the PKD1 and PKD2 genes) primarily affecting adults." (PMID 39125479, 2024). "PKD2 was identified by Mochizuki in 1996 from three family lineages of autosomal dominant polycystic kidney disease (ADPKD) patients." (PMID 39451240, 2024). "In autosomal dominant polycystic kidney disease (ADPKD), pancreatic cysts are a marker of being 5.9 times more likely to have the PKD2 instead of the PKD1 mutation." (PMID 39058059, 2024). "Autosomal dominant polycystic kidney disease (ADPKD), caused by mutations in the polycystin-1 (PKD1) or polycystin-2 (PKD2) genes, is the most common life-threatening monogenic disease, affecting at least 1:1,000 individuals worldwide." (PMID 38095025, 2024). "Autosomal dominant polycystic kidney disease (ADPKD) occurs when the proteins Polycystin-1 (PC1, PKD1) and Polycystin-2 (PC2, PKD2) contain mutations." (PMID 38607049, 2024). "Autosomal Dominant Polycystic Kidney Disease (ADPKD) is primarily caused by mutations in the PKD1 (85%) or PKD2 gene (15%), which affect the glycoproteins polycystin 1 (PC1) and polycystin 2 (PC2), respectively." (PMID 38671609, 2024). "PKD2 mutations cause Autosomal Dominant Polycystic Kidney Disease (ADPKD)." (PMID 39408938, 2024). "Autosomal dominant polycystic kidney disease (ADPKD) is the most common genetic disease, which is caused by mutations in PKD1 and PKD2 genes, encoding for polycystin-1 and polycystin-2 proteins, respectively." (PMID 39456148, 2024).
autosomal dominant polycystic kidney disease (continued). "Autosomal dominant polycystic kidney disease (ADPKD) is one of the causes of end-stage renal disease and is caused by a polycystic protein-1 (PKD1) or PKD2 gene mutation." (PMID 37739961, 2023). "Autosomal dominant polycystic kidney disease (ADPKD) is an inherited cystic pathology consequent to mutations in the multipass transmembrane proteins polycistin-1 and polycistin-2, encoded respectively by Pkd-1 and Pkd-2 genes." (PMID 37842748, 2023). "Autosomal dominant polycystic kidney disease (ADPKD) is the most common monogenic cause of kidney failure in adults and is due to pathogenic variants in either PKD1 or PKD2." (PMID 37507763, 2023). "Autosomal dominant polycystic kidney disease (ADPKD) is the most common inherited KD, due to mutations in the polycystic kidney disease 1 and 2 (PKD1 or PKD2) genes." (PMID 37762196, 2023). "We used specific agonists, including triptolide, ATP, 4-chloro-orto-cresol for polycystic kidney disease 2 (PKD2), inositol 1,4,5‐trisphosphate receptors (IP3Rs), and ryanodine receptors, respectively." (PMID 37523531, 2023). "The calcium-permeable cation channel Amo, homologous to human PKD2, which is causative of Autosomal Dominant Polycystic Kidney Disease (ADPKD), has previously been shown to maintain calcium homeostasis downstream of Simu during later stages of efferocytosis in Drosophila." (PMID 38283366, 2023). "Autosomal dominant polycystic kidney disease (ADPKD), due to pathogenic variants in PKD1 or PKD2 genes, is generally an adult-onset disorder which commonly progresses to kidney failure." (PMID 40225160, 2023). "Autosomal dominant polycystic kidney disease (ADPKD) is mainly caused by mutations in two main genes, PKD1 (OMIM#: 601313) and PKD2 (OMIM#: 173910)." (PMID 35327948, 2022). "Inhumans, dysfunction of PKD2 or its most common interacting partner PKD1 leads to nearly all cases of Autosomal Dominant Polycystic Kidney disease (ADPKD)." (PMID 35359441, 2022). "Autosomal dominant polycystic kidney disease (ADPKD) is caused by mutations of the PKD1 or PKD2 genes, which encode the proteins polycystin-1 (PC1) and polycystin-2 (PC2), respectively." (PMID 36406261, 2022). "The same disease can be caused by different genes, and this could influence the outcome (i.e., mutations in PKD1 are associated with earlier ESRD than PKD2 in autosomal dominant polycystic kidney disease [ADPKD]); this is known as genetic heterogeneity." (PMID 35207681, 2022). "Autosomal dominant polycystic kidney disease (PKD) is commonly inherited as a heterozygous, loss-of-function mutation in either PKD1 or PKD2, which encode the proteins polycystin-1 (PC1) or polycystin-2 (PC2), respectively." (PMID 36564419, 2022). "Autosomal dominant polycystic kidney disease (ADPKD) affects approximately 12 million people worldwide and is mostly due to inherited mutations in either PKD1 or PKD2 genes." (PMID 36293397, 2022). "Autosomal dominant polycystic kidney disease (ADPKD), as one of the most common inherited kidney diseases, is caused by mutations of PKD1 or PKD2 gene." (PMID 33809516, 2021). "Autosomal dominant polycystic kidney disease (ADPKD), occurring due to PKD1 and PKD2 mutations, have been identified more than three decades ago." (PMID 34440002, 2021). "Autosomal-dominant polycystic kidney disease (ADPKD) is considered the most common monogenic-inherited kidney disease, mainly caused by mutations in either PKD1 (~85%) or PKD2 (~15%) with an incidence estimated to be ~1 in 10001." (PMID 34315885, 2021). "Mutations in PKD2 cause autosomal dominant polycystic kidney disease (ADPKD)." (PMID 34095129, 2021). "Autosomal dominant polycystic kidney disease (ADPKD, caused by variants in PKD1 and PKD2) is the most common inherited kidney disorder, is the fourth leading cause of chronic kidney disease, and is often not diagnosed until later stages of the disease." (PMID 34385667, 2021).
autosomal dominant polycystic kidney disease (continued). "In autosomal dominant polycystic kidney disease (ADPKD), the majority of mutations occur in PKD1 and PKD2, which encode polycystin 1 and polycystin 2, which form a complex and function at the primary cilium." (PMID 34095126, 2021). "Several recent studies reported that autosomal dominant polycystic kidney disease (ADPKD) is mainly caused by mutations in the PKD1 and PKD2 genes and rarely by mutations in the GANAB gene." (PMID 32550232, 2020). "Autosomal dominant polycystic kidney disease (ADPKD) is the consequence of a heterozygous mutation in one of two genes: PKD1 on chromosome 16, in 80-85% of cases, or PKD2 on chromosome 4." (PMID 31309115, 2019). "Autosomal dominant polycystic kidney disease (ADPKD) is the most common genetic renal disease, caused in the majority of the cases by a mutation in either the PKD1 or the PKD2 gene." (PMID 31773180, 2019). "Polycystic kidney disease 1 (PKD1) and PKD2 are genes responsible for encoding polycystin 1 and polycystin 2 respectively, and loss-of-function of PKD1 and PKD2 genes can result in autosomal dominant polycystic kidney disease in subsequent generations." (PMID 31757932, 2019). "For instance, the onset and progression of autosomal dominant polycystic kidney disease (ADPKD) is commonly explained as an effect of the dysregulated expression of the PKD1 or PKD2 genes." (PMID 30692602, 2019). "Autosomal dominant polycystic kidney disease (ADPKD), caused by mutations in either PKD1 or PKD2 genes, is one of the most common human monogenetic disorders and the leading genetic cause of end-stage renal disease." (PMID 31515477, 2019). "HNF1B is known to regulate transcription of polycystic kidney and hepatic disease (PKHD1), uromodulin (UMOD) and polycystic kidney disease 2 (PKD2)." (PMID 29576871, 2018). "Autosomal dominant polycystic kidney disease (ADPKD), the commonest inherited kidney disease, is generally caused by heterozygous mutations in PKD1, PKD2, or GANAB (PKD3)." (PMID 30333007, 2018). "Most notably, this gene/protein family is named after PKD because mutations in either PKD1 or PKD2 account for all of the known forms of Autosomal Dominant Polycystic Kidney Disease (ADPKD), which is the most common genetic cause and the fourth most common cause of kidney failure." (PMID 28271061, 2017). "Autosomal Dominant Polycystic Kidney Disease (ADPKD) arises from mutations to either polycystin 1 or 2 (PC1 or PC2, gene name Pkd1 and Pkd2)." (PMID 27081851, 2016). "Genetic testing of PKD1 and PKD2 is expected to play an increasingly important role in determining allelic influences in autosomal dominant polycystic kidney disease (ADPKD) in the near future." (PMID 27835667, 2016). "Mutations in PKD2 and PKD1, which binds to and complexes with PKD2, result in human autosomal dominant polycystic kidney disease." (PMID 25660539, 2015). "Polycystin-2 (PC2), encoded by the PKD2 gene, is mutated in ~15% of autosomal dominant polycystic kidney disease." (PMID 25861040, 2015). "Autosomal dominant polycystic kidney disease (ADPKD), an inherited syndrome affecting 1∶400–1,000 individuals, arises from mutations in the PKD1 or PKD2 genes, encoding the polycystins." (PMID 25474361, 2014). "Examples of cilia-related genes with orthologs in both C. elegans and humans include PKD-2 (polycystic kidney disease-2)/PC2 (polycystin 2) and LOV-1(location of vulva defective-1)/PC1 (polycystin 1)." (PMID 25486278, 2014). "Polycystic liver disease (PLD) occurs in 75–90% of patients affected by autosomal dominant polycystic kidney disease (ADPKD), which affects 1∶400–1,000 adults and arises from inherited mutations in the PKD1 or PKD2 genes." (PMID 25474361, 2014). "Autosomal dominant polycystic kidney disease (ADPKD), the most common form of PKD, is caused by mutation of PKD1 or PKD2, which encode the proteins polycystin-1 or polycystin-2, respectively." (PMID 23536832, 2013).